TRIT1 (tRNA isopentenyltransferase 1)
Description:
Catalyzes the transfer of a dimethylallyl group onto the adenine at position 37 of both cytosolic and mitochondrial tRNAs, leading to the formation of N6-(dimethylallyl)adenosine (i6A37). Mediates modification of a limited subset of tRNAs: tRNA(Ser)(AGA), tRNA(Ser)(CGA), tRNA(Ser)(UGA), as well as partial modification of the selenocysteine tRNA(Ser)(UCA). TRIT1 is therefore required for selenoprotein expression.
Synonyms: IPPT; IPTase; IPT; MOD5; FLJ20061; COXPD35; GRO1; hGRO1
Tractability: PROTAC: ubiquitination databases record sites on it.
Gene: Protein-coding gene on chromosome 1 (39,838,110 to 39,883,511, reverse strand). Ensembl gene ENSG00000043514.
Subcellular location: Mitochondrion (Isoform 1); Mitochondrion (Isoform 4); Cytoplasm (Isoform 2); Cytoplasm (Isoform 3); Cytoplasm (Isoform 5)
Subcellular location (Human Protein Atlas): Mitochondria
Pathways (Reactome):
Metabolism of RNA: tRNA modification in the mitochondrion; tRNA modification in the nucleus and cytosol
Gene Ontology:
Molecular function: tRNA dimethylallyltransferase activity; ATP binding; nucleic acid binding; zinc ion binding
Biological process: mitochondrial tRNA modification; tRNA modification; tRNA processing
Cellular component: mitochondrion; mitochondrial matrix; cytoplasm
Genetic constraint (gnomAD): Loss-of-function variants: 37 observed, 48.4 expected, observed/expected ratio (o/e) 0.76, 90% interval 0.59 to 1.01. The upper end of that interval is the gene's LOEUF score, 1.01, which puts it in group 4 of 6, group 1 being the genes least tolerant of losing a copy. Missense variants: 510 observed, 588.09 expected, observed/expected ratio (o/e) 0.87, 90% interval 0.81 to 0.93. Synonymous variants: 180 observed, 209.53 expected, observed/expected ratio (o/e) 0.86, 90% interval 0.76 to 0.97.
Gene-disease validity (ClinGen):
ClinGen rates the evidence that TRIT1 causes each of these diseases.
mitochondrial disease (autosomal recessive): Definitive.
Homologues: Orthologues: chimpanzee TRIT1 (99% identical), macaque TRIT1 (96% identical), rabbit TRIT1 (91% identical), mouse Trit1 (89% identical), pig TRIT1 (89% identical), rat Trit1 (88% identical), guinea pig TRIT1 (87% identical), dog TRIT1 (82% identical), tropical clawed frog trit1 (61% identical), zebrafish trit1 (57% identical), Drosophila melanogaster CG31381 (37% identical), Caenorhabditis elegans gro-1 (30% identical).
Diseases named in the same sentence as TRIT1 in open-access papers:
TRIT1 is named in the same sentence as 36 diseases in open-access papers, as found by Europe PMC text mining. Sharing a sentence is not in itself a finding about the gene and the disease. The quoted sentences say what the papers report.
lung carcinoma (4 papers, 2014 to 2021). "One variant of TRIT1, TRIT1-F202L, was found to predict poor survival among patients with lung cancer." (PMID 34361072, 2021). "An allele that encodes TRIT1-F202L was later found to be associated with modulation of lung cancer survival and was reported to be active for cy-tRNATyrUAA-TMS in S. cerevisiae using a high level expression plasmid system." (PMID 32324744, 2020). "It is also worth noting that TRIT1 has been reported as a tumor suppressor and certain rare variant alleles are associated with poor survival from lung cancer in some ethnic groups; other mitochondrial-disease associated genes such as GRIM19 have also been implicated as a tumor suppressor." (PMID 24901367, 2014). "A mouse study shows that TRIT1 mRNA is downregulated in lung cancer cells, while its overexpression decreases the rates of lung tumor development." (PMID 34361072, 2021).
small cell lung carcinoma (4 papers, 2021 to 2025). Small cell lung cancer (SCLC) is a highly aggressive malignant neoplasm, accounting for 10-15% of lung cancer cases, characterized byrapid growth, and early metastasis. "Overall, our results show that the tRNA modifier gene TRIT1 undergoes gene amplification-associated overexpression in small-cell lung cancer cell lines and primary samples." (PMID 33919717, 2021). "Once we had demonstrated the existence of TRIT1 gene amplification-associated overexpression in small-cell lung cancer cell lines, we interrogated its role in in vivo tumor growth and its impact on i6A-tRNA-associated activity." (PMID 33919717, 2021). "Data-mining of the available RNA expression patterns in the described set of small-cell lung cancer cell lines demonstrated that TRIT1 gene amplification was associated with the overexpression of its mRNA." (PMID 33919717, 2021). "Herein, we describe how TRIT1 undergoes gene amplification-associated overexpression in cancer cell lines and primary samples of small-cell lung cancer, giving rise to growth-inhibitory sensitivity to arsenic trioxide." (PMID 33919717, 2021). "Herein, we show that TRIT1 undergoes gene amplification-associated overexpression in cancer cell lines and primary samples of small-cell lung cancer." (PMID 33919717, 2021). "Moreover, our group has found that TRIT1 undergoes gene amplification-associated overexpression in small cell lung cancer (SCLC) that promotes tumor growth." (PMID 37369946, 2023). "In small-cell lung cancer, we would like to propose that the gene amplification-associated overexpression of the tRNA modifier TRIT1 could be an optimal bona fide target candidate in this context." (PMID 33919717, 2021). "For non-small-cell lung cancer, preclinical in vitro data suggest its potential antitumor role, but it can be in the setting of small-cell lung cancer with the use of TRIT1 gene amplification as an associated biomarker in which its true therapeutic value for solid malignancies may be revealed." (PMID 33919717, 2021). "Most notably, the presence of TRIT1 gene amplification was associated with the overexpression of the TRIT1 protein in the DMS-273 and HCC-33 small-cell lung cancer cell lines determined by western-blot and immunocytochemistry." (PMID 33919717, 2021). "TRIT1 gene amplification was observed in 14.7% (10/68) of primary small-cell lung cancer cases in this dataset." (PMID 33919717, 2021). "We also wondered about the distribution of TRIT1 gene amplification according to the small-cell lung cancer molecular subtypes ASCL1, NEUROD1, POU2F3, and YAP1." (PMID 33919717, 2021). "Overall, our results indicate a role for TRIT1 as a small-cell lung cancer-relevant gene that, when undergoing gene amplification-associated activation, can be targeted with the differentiation agent arsenic trioxide." (PMID 33919717, 2021). "Although there are no publicly available small compound inhibitors of TRIT1 enzymatic activity, arsenic trioxide, through its direct effects on selenium-containing proteins, is potentially effective in small-cell lung cancer cells with high levels of TRIT1." (PMID 33919717, 2021). "Exploring new pathways for targeted therapy, we have observed that extra-copies of the tRNA modifier TRIT1, involved in the translation of selenoproteins, confers sensitivity to arsenic trioxide in small-cell lung cancer." (PMID 33919717, 2021). "Notably, TRIT1 is also an emerging candidate oncogene, as its high expression has been reported in small cell lung cancer." (PMID 40391218, 2025). "We identified TRIT1 gene amplification in 10.3% (4/39) of primary small-cell lung cancer cases." (PMID 33919717, 2021). "However, the TRIT1 gene was found to be amplified in 18.3% (11 of 60) of small-cell lung cancer cell lines." (PMID 33919717, 2021).
small cell lung carcinoma (continued). "Importantly, cancer cells with TRIT1 gene amplification were more sensitive to the drug arsenic trioxide, which provided a theoretical basis for the clinical treatment of such small cell lung cancer patients." (PMID 34660690, 2021). "In addition to expanding the role of the epitranscriptome in tumorigenesis, illustrated here by the described tRNA modification, another aspect of the TRIT1 gene amplification in small-cell lung cancer might have an additional impact on the treatment of this malignancy." (PMID 33919717, 2021). "The occurrence of TRIT1 gene amplification was not an event confined to in vitro-grown small-cell lung cancer cell lines, but was also observed in primary tumor samples." (PMID 33919717, 2021).
melanoma (2 papers, 2021 to 2024). A malignant, usually aggressive tumor composed of atypical, neoplastic melanocytes. "Furthermore, a peptide originating from the reverse strand in the 3′-UTR of tRNA isopentenyltransferase 1 (TRIT1) serves as an antigen or sensitizes HLA-B57+ melanoma cells to lysis by cytotoxic T lymphocyte." (PMID 39333489, 2024). "Interestingly, the 3′-untranslated region of TRIT1 contains an open reading frame in the amplified region that generates a peptide recognized by cytotoxic T lymphocytes, leading to the lysis of melanoma cells." (PMID 33919717, 2021).
epilepsy (1 paper, 2015). A brain disorder characterized by episodes of abnormally increased neuronal discharge resulting in transient episodes of sensory or motor neurological dysfunction, or psychic dysfunction. "Epilepsy was also noted in patients with the m.12147G>A, m.8993T>G, and recessive TRIT1 mutations." (PMID 26381753, 2015).
esophageal cancer (1 paper, 2025). A primary or metastatic malignant neoplasm involving the esophagus. "The pan-cancer analysis results indicate that the expression level of TRIT1 is generally higher in various tumors such as esophageal cancer, gastric adenocarcinoma and rectal cancer than in normal tissues." (PMID 40391218, 2025).
fibrolamellar carcinoma (1 paper, 2025). "The expression level of TRIT1 in hepatocellular carcinoma is higher than that in fibrolamellar carcinoma." (PMID 40391218, 2025).
gastric cancer (1 paper, 2026). A primary or metastatic malignant neoplasm involving the stomach. "It was recently reported that several tagging SNPs and haplotypes in TRIT1 were significantly associated with a risk and clinicopathological features of gastric cancer in a Chinese population." (PMID 41516419, 2026).
hepatoma (1 paper, 2025). "Experimental validation confirmed significantly differential TRIT1 expression between hepatocellular carcinoma (LIHC) and normal liver tissues." (PMID 40391218, 2025). "Initial experiments involved quantitative PCR (qPCR) analysis comparing TRIT1 expression levels between established human hepatocellular carcinoma cell lines and normal human hepatic stellate cells." (PMID 40391218, 2025). "This investigation employed the TCGA database to systematically analyze TRIT1 expression patterns in hepatocellular carcinoma." (PMID 40391218, 2025). "This study provides the first evidence that the presence of TRIT1 can serve as a reliable marker for diagnosis and prognostication of hepatocellular carcinoma." (PMID 40391218, 2025). "Moreover, TRIT1 emerges as a critical indicator of the potential for cancer infiltration and invasion of the immune system, holding significant implications for the development of targeted therapies for hepatocellular carcinoma." (PMID 40391218, 2025). "Therefore, it is reasonable to infer that TRIT1 may affect the energy metabolism of hepatoma cells by regulating the expression of selenoprotein, affecting their growth and survival ability." (PMID 40391218, 2025).
Infertility (1 paper, 2018). "The biological processes significantly represented among differentially expressed genes included mitochondrial function (Mrps31 and Trit1), cell senescence (Gpx6, Lamtor1 and Hist1h1e), cell growth (Hormad1 and Hormad2), infertility (Sycp3), and embryo development (Gli3)." (PMID 29851234, 2018).
leukemia (1 paper, 2021). A malignant (clonal) hematologic disorder, involving hematopoietic stem cells and characterized by the presence of primitive or atypical myeloid or lymphoid cells in the bone marrow and the blood. "The effect of arsenic trioxide in APL involves inducing differentiation of the leukemia cells, the “differentiation” category being the most overrepresented in the GO analysis of TRIT1-disrupted cells." (PMID 33919717, 2021).
liver cancer (1 paper, 2025). An epithelial or non-epithelial malignant neoplasm that arises from the liver. "The study was designed to explore potential applications of TRIT1 in early diagnostic strategies and prognostic evaluation for liver cancer." (PMID 40391218, 2025). "However, it is important to note that the correlation between the DNA methylation level of TRIT1 and the prognosis of liver cancer lacks statistical significance, and the underlying mechanism remains incompletely understood." (PMID 40391218, 2025). "A comprehensive analysis using experimental techniques to assess the level and significance of TRIT1 in liver cancer tissues were performed." (PMID 40391218, 2025). "The findings offer novel understanding of TRIT1’s role in liver cancer and identify potential therapeutic targets for the treatment of this disease." (PMID 40391218, 2025). "Given TRIT1’s role in the immune microenvironment of liver cancer, it emerges as a potential target for immunotherapy." (PMID 40391218, 2025). "This study additionally revealed a correlation between elevated TRIT1 expression and unfavorable clinicopathological markers of liver cancer." (PMID 40391218, 2025). "The experimental results demonstrated consistent overexpression patterns with initial observations, and qPCR data confirmed that the expression level of TRIT1 in liver cancer tissues was significantly increased compared with neighboring normal tissues." (PMID 40391218, 2025). "Future investigations should delve into the precise manner in which TRIT1 methylation influences its expression and how this influence manifests in the clinical presentation of liver cancer." (PMID 40391218, 2025). "ROC curve analysis further demonstrated that TRIT1 gene expression exhibited high predictive accuracy for liver cancer, with an AUC value of 0.854." (PMID 40391218, 2025). "The results showed that TRIT1 expression was significantly upregulated in liver cancer cell lines compared to normal cell lines." (PMID 40391218, 2025). "The significance of the liver cancer immune microenvironment in treatment underscores the need for further exploration and understanding of TRIT1’s role in this context." (PMID 40391218, 2025). "This suggests that the high expression of TRIT1 might have a dual - edged effect on the growth of liver cancer cells through selenoproteins." (PMID 40391218, 2025). "Given TRIT1’s subcellular specificity, it could serve as a potential therapeutic target for liver cancer." (PMID 40391218, 2025). "This suggests that TRIT1 may influence the immune microenvironment of liver cancer by inhibiting the infiltration of certain immune cells while promoting the accumulation of others." (PMID 40391218, 2025). "In conclusion, the high expression of TRIT1 in liver cancer may have a significant impact on various cellular processes, including metabolism, proliferation, energy production, and drug sensitivity, by modulating the expression and function of selenoproteins." (PMID 40391218, 2025). "Hypermethylation at specific TRIT1 loci was hypothesized to regulate gene expression patterns, potentially leading to a poor prognosis in liver cancer." (PMID 40391218, 2025). "The development of treatment strategies that specifically target TRIT1’s mitochondrial and cytoplasmic functions could offer novel avenues for liver cancer management." (PMID 40391218, 2025). "Additionally, relevant studies have established prognostic models for liver cancer patients, reinforcing the findings and highlighting the importance of understanding TRIT1’s role in the immune microenvironment." (PMID 40391218, 2025). "Furthermore, considering the dynamic shifts in methylation levels, further exploration is warranted to assess TRIT1’s role in different stages of liver cancer and its potential integration into clinical decision-making processes." (PMID 40391218, 2025).
liver cancer (continued). "Although this study offers a novel perspective on the correlation between TRIT1 levels and prognosis in patients with liver cancer (LIHC), several notable limitations exist that could potentially affect the reliability and generalizability of the findings." (PMID 40391218, 2025). "In addition, the high expression of TRIT1 in liver cancer may also be related to the abnormal metabolism of liver cancer cells." (PMID 40391218, 2025). "By affecting the expression of selenium protein, TRIT1 may affect the proliferation and cell cycle process of liver cancer cells, which can not only promote the growth of normal cells, but also inhibit the proliferation of cancer cells, even inducing their apoptosis." (PMID 40391218, 2025). "Therefore, TRIT1 expression could serve as a valuable addition to the existing panel of biomarkers for liver cancer diagnosis." (PMID 40391218, 2025). "Through this research, we aim to not only elucidate the mechanistic role of TRIT1 in LIHC pathogenesis but also to provide novel insights and potential therapeutic targets for the diagnosis and treatment of liver cancer." (PMID 40391218, 2025).
major depressive disorder (1 paper, 2021). An episode of depression lasting two or more weeks without an intervening episode of mania. "TRIT1 has been known as a tumor suppressor for several forms of cancer, and its pleiotropy between LOAD and major depressive disorder or cardiovascular risk factor has been previously noted." (PMID 34873149, 2021).
Mitochondrial myopathy (1 paper, 2014). "Thus we decided to further investigate a previously reported patient with mitochondrial myopathy due to a pathogenic (m.7480A>G) mutation at position 38 in mt-tRNASer(UCN), a substrate of TRIT1." (PMID 24901367, 2014).
myoclonic epilepsy (1 paper, 2025). A group of epilepsy syndromes in which myoclonic seizures are a prominent feature. "Phenotypes caused by defects in TRIT1, such as myoclonic epilepsy and delayed speech, may reflect its importance in maintaining cell homeostasis." (PMID 40391218, 2025).